MYO10 (myosin X)
Diseases named in the same sentence as MYO10 in open-access papers (continued):
Sharing a sentence is not in itself a finding about the gene and the disease.
brain tumors (1 paper, 2024). "Some of the frequently mutated genes have been rarely reported in brain tumors according to the COSMIC database: EPH2B (67% vs 1.11%), DICER1 (67 vs 1.25%), KMT2B (67% vs 1.46%), ATRX (67% vs 13.95%) as well as several muscular genes (DMD, MYO10, MYO9B, MYH6) (P < .00001, Fischer exact test)." (PMID 39233831, 2024).
Breast Invasive Carcinoma (1 paper, 2016). "Using cBioPortal, we determined that increased MYO10 levels strongly correlates with increased Src mRNA levels in the Breast Invasive Carcinoma data set (Log Odds ratio: 0.826; P value, <0.001)." (PMID 27910855, 2016).
colon cancer (1 paper, 2021). "In colon cancer cell lines, MYO10 expression was upregulated by signaling through the protease-activated receptor-2, and activity of this motor mediated protease-activated receptor-2 agonist-driven migration of cancer cells." (PMID 33670106, 2021). "Since expression of both DCC and MCC is known to be decreased in CRC, it is tempting to speculate that depletion of these binding partners and regulators could markedly affect MYO10 functions in colon cancer cells." (PMID 33670106, 2021).
colorectal adenocarcinoma (1 paper, 2022). The most common type of colorectal carcinoma. "We also found a positive correlation between KITENIN and Myo10 expression in colorectal adenocarcinoma in TCGA." (PMID 35853101, 2022). "Furthermore, a positive correlation was found between the expression of KITENIN and that of Myo10 in colorectal adenocarcinoma of The Cancer Genome Atlas (TCGA)." (PMID 35853101, 2022).
colorectal tumours (1 paper, 2022). "Because the downregulation of Myo10 is responsible for the therapeutic action of KDIP on colorectal tumours with higher KITENIN expression, we propose that KDIP could be used as a dual blocker to the oncogenic function of both KITENIN and Myo10 proteins." (PMID 35853101, 2022).
Duchenne muscular dystrophy (1 paper, 2021). Duchenne muscular dystrophy (DMD) is a neuromuscular disease characterized by rapidly progressive muscle weakness and wasting due to degeneration of skeletal, smooth and cardiac muscle. "Myo10 immunoreactivity in regions of dystrophin-deficient skeletal muscle samples from (A) mdx mice and (B) Duchenne muscular dystrophy (DMD) patients that are undergoing active regeneration." (PMID 34519272, 2021). "In vivo, Myo10 labels regenerating muscle fibers associated with Duchenne muscular dystrophy and acute muscle injury." (PMID 34519272, 2021).
epilepsy (1 paper, 2023). A brain disorder characterized by episodes of abnormally increased neuronal discharge resulting in transient episodes of sensory or motor neurological dysfunction, or psychic dysfunction. "This group of patients also have high-frequency mutations of MYO10 and ADGRL3, which may facilitate precise early screening of PCOS in female patients with epilepsy." (PMID 40217327, 2023).
esophageal carcinoma (1 paper, 2023). A primary or metastatic malignant neoplasm involving the esophagus. "Looking for esophageal carcinoma susceptibility in OMIM, we found listed at #133239 RNF6 and DCC; the latter, according to the STRING database, is linked by experiments/co-expression/co-occurrence to TRIO (5p15.2)(a) and MYO10 (5p15.1)(p)." (PMID 38248360, 2023).
gastric cancer (1 paper, 2024). A primary or metastatic malignant neoplasm involving the stomach. "Interestingly, we could not detect the actin motor myosin 10 (MYO10), which regulates the formation and elongation of filopodia on WNT7A-positive dendritic filopodia, suggesting a difference from the Wnt8a cytonemes observed in zebrafish gastrulation or WNT3 cytonemes in human gastric cancer." (PMID 39576204, 2024).
glaucoma (1 paper, 2022). Increased pressure in the eyeball due to obstruction of the outflow of aqueous humor. "Because actin dynamics are impaired in glaucoma TM cells, Myo10 may be expressed longer on glaucomatous filopodia." (PMID 35573666, 2022). "This may explain increased Myo10 protein levels in mechanically stretch glaucoma cells." (PMID 35573666, 2022). "Finally, mechanical stretch caused a small, yet significant increase in Myo10 protein levels in glaucoma cells, but did not affect cellular communication of fluorescent vesicles via filopodia-like tunneling nanotubes." (PMID 35573666, 2022).
glioblastoma (1 paper, 2025). The most malignant astrocytic tumor (WHO grade IV). "Second, the lifespan of mice with glioblastoma was shown to be extended significantly on a Myo10 KO background." (PMID 40440343, 2025).
kidney carcinoma (1 paper, 2012). Primary or metastatic malignant neoplasm involving the kidney. "Myo10 is known as a molecular motor, which has been shown to promote filopodia extension under the modulation of PtdIns P3 in COS 7 kidney carcinoma cells." (PMID 22590642, 2012).
laryngeal carcinoma (1 paper, 2022). Carcinoma that arises from the laryngeal epithelium. "To explore the role of Myosin X in the metastasis of laryngeal cancer, we examine both the mRNA and protein level of Myosin X in LSCC tissues." (PMID 35951144, 2022).
lung carcinoma (1 paper, 2018). "Our analysis of a cohort of 362 lung cancer patients, including 151 LUSC patients, revealed that the MYO10 mRNA expression ratio between tumor and adjacent tumor-free tissues is an independent prognostic factor that is associated with poor overall survival in patients with resected LUSC." (PMID 29934580, 2018).
neuromyelitis optica spectrum disorder (1 paper, 2024). "Proof of concept for this hypothesis has been provided, for example, by antibodies against glucose-regulated protein 78 (GRP78) in addition to aquaporin 4 (AQP4) in patients with neuromyelitis optica spectrum disorder (NMOSD) or antibodies against unconventional Myosin-X in NMDAR encephalitis." (PMID 39142424, 2024).
Sepsis (1 paper, 2025). Sepsis is defined as life-threatening organ dysfunction caused by a dysregulated host response to infection. "For example, the genomic stability regulation of MYO10 may be associated with apoptosis resistance caused by mitochondrial damage in immune cells during sepsis, while the metabolic modification function of SULT1B1 may be involved in sepsis-related disorders of adrenocortical hormone metabolism." (PMID 41246299, 2025). "The point of MYO10 was the highest indicated that MYO10 had the greatest impact on the predictive value of sepsis and the result was significant (P < 0.05)." (PMID 41246299, 2025). "In summary, these biomarkers may be involved in sepsis through mechanisms related to cell cycle regulation (MYO10, MKI67), metabolic reprogramming (SULT1B1), and inflammatory signal transduction (CREB5)." (PMID 41246299, 2025). "Additionally, evaluating the efficacy of small-molecule inhibitors targeting CREB5 or MYO10 in sepsis models may provide a theoretical basis for developing novel therapies targeting immune metabolism or cell cycle regulation." (PMID 41246299, 2025). "This study obtained a total of 4 biomarkers (MYO10, SULT1B1, MKI67, and CREB5), and the analysis of nomogram showed that the biomarkers had good clinical predictive value to sepsis." (PMID 41246299, 2025). "This study identified 4 biomarkers, namely MYO10, SULT1B1, MKI67, and CREB5 and explored the pathogenesis of sepsis, providing new insights for potential treatment strategies by integrating transcriptomic data and single-cell analysis." (PMID 41246299, 2025). "The RT-qPCR results showed the expression of MYO10, SULT1B1, MKI67, and CREB5 had significant differences between controls and sepsis samples (P < 0.05)." (PMID 41246299, 2025). "The potential mechanisms of the four biomarkers (MYO10, SULT1B1, MKI67, CREB5) identified in this study in sepsis can be preliminarily interpreted through their known functions and related pathways." (PMID 41246299, 2025).
syphilis (1 paper, 2025). A contagious bacterial infection caused by the spirochete Treponema pallidum. "This study reveals a novel RNA splicing‐mediated dissemination mechanism, proposing CSRP1/MYO10 as therapeutic targets to limit bacterial dissemination in syphilis." (PMID 40666038, 2025).
vocal cord polyp (1 paper, 2022). "To investigate the expression of Myosin X and its implication in the metastasis of LSCC, we recruited 30 patients with LSCC and 6 patients with vocal cord polyp range from October 2016 to October 2018." (PMID 35951144, 2022).
cancer (25 papers, 2013 to 2026). A tumor composed of atypical neoplastic, often pleomorphic cells that invade other tissues. "Abundant filopodia are characteristic of invasive cancer cells and high expression of filopodia regulators such as fascin and myosin-X are associated with cancer progression." (PMID 40185977, 2025). "Increasing experimental data shows that myosin X is implicated in cancer cell's protrusions and metastasis development by transporting β1 integrins to the filopodia tips." (PMID 27121062, 2016). "Thus it is possible that the CDH18 gene and other nearby genes identified in cohort (including CTNND2, CDH12 and MYO10) play a mechanistic role in the observed connection between MetS and cancer risk." (PMID 23628382, 2013). "Increasing attention has been directed toward filopodia and filopodium-like protrusions (FLPs) in cancer research, since overexpression of proteins such as fascin-1, myosin X, and formin enhances metastatic cell motility and invasiveness." (PMID 41011506, 2025). "We previously showed that TLNRD1 and ITGB1BP1 accumulate at the tips of myosin-X (MYO10)-induced filopodia in cancer cells." (PMID 39013281, 2024). "Myosin-X (MYO10), a homodimeric molecular motor, is critical for promoting cancer cell invasion by inducing filopodia formation." (PMID 39309444, 2024). "For instance, cancer development-related PI3K-Akt signaling, focal adhesion signaling, integrin-ECM pathways, and EMT processes were all enriched in MYO1B/MYO5A/MYO10 associated DEGs." (PMID 35478939, 2022). "The KITENIN‐interacting protein myosin‐X (Myo10), which has oncogenic activity in several cancers, functioned as an effector to stabilize the KITENIN homodimer in the cis formation." (PMID 35853101, 2022). "Collectively, our present results provide a new cancer therapeutic peptide for blocking colorectal liver metastasis, which acts by inducing the downregulation of Myo10 and specifically targeting the stability of the oncogenic KITENIN protein." (PMID 35853101, 2022). "For instance, epigenetic heterogeneity and JAG1 signaling were recently shown to jointly promote the persistence of filopodia via the MYO10 in invading cancer cells." (PMID 34831307, 2021). "Specifically, Myo10 is upregulated in several cancers, is a key component of invadopodia, and inhibiting it suppresses invasion." (PMID 29229982, 2017). "A feature common to metastatic human cancers suggests that myosin X could drive metastasis of multiple cancer types." (PMID 41011506, 2025). "These and other studies showing that Myo10-positive filopodia promote the migration of metastatic cancer cells, together with the data presented here, provide strong justification for performing screens to identify inhibitors of Myo10 as possible cancer therapeutics." (PMID 40440343, 2025). "More generally, many cancer cell types exhibit elevated levels of Myo10, which may support their growth by promoting SNCC." (PMID 40440343, 2025). "To determine whether TRPC5 modulates cancer cell motility via filopodia formation, we observed that ML-204 markedly suppresses MYO10-induced filopodia in MKN-45 and DLD-1 cells in a concentration-dependent manner." (PMID 39309444, 2024). "In neurons, MYO10 binds to a cell surface receptor called “deleted in colorectal cancer” (DCC)." (PMID 33670106, 2021).
cancer (continued). "Here, we study filopodia induced by overexpression of myosin X, typical for cancer cells." (PMID 31399564, 2019). "Loss of Myo10 may well have additional effects on vascular patterning, and given the importance of angiogenesis in development, cancer, and eye disease, further investigation of the roles of Myo10 and filopodia in angiogenesis is warranted." (PMID 29229982, 2017). "Growing evidence indicates that Myo10 has important roles in cancer biology." (PMID 29229982, 2017). "In addition, upregulation of MYO10 expression lead to filopodia formation and was sufficient to drive cancer cell invasion in non-invasive cell lines in a CCB sensitive manner." (PMID 27910855, 2016). "These and other results can inform efforts to target Myo10 and HSET to selectively kill cancer cells by increasing their frequency of multipolar divisions." (PMID 40440343, 2025). "Consistent with previous reports about the elevated expression in other cancers, MYO1B, MYO5A, and MYO10 levels were increased in HNSCC tissues compared with adjacent normal tissues whereas MYO5C expression was found to be downregulated." (PMID 35478939, 2022). "Our analysis identified the TGFβ-inducible non-muscle MYO10 as an essential mediator of TGFβ-regulated cancer cell invasion." (PMID 29934580, 2018). "Thus, MYO10 expression facilitates filopodia formation and invasion whereas inhibition of L-type calcium channels using CCBs or inhibition of PI3K impedes filopodia formation, directional cell migration and cancer cell invasion." (PMID 27910855, 2016). "Taken together, these observations strongly support that MYO10, MYH9 and MYO1E play essential and non-redundant roles in the functionality of the invasion machinery in cancer." (PMID 29934580, 2018).
tumor (15 papers, 2013 to 2024). "Interestingly, in addition to MYO10 c.1511C>T (A504V), II-1 in Family F carried a somatic tumor mutation MYO10 c.745C>T (R249X)." (PMID 38773237, 2024). "Evidence has shown MYO10 promotes tumor progression by inducing genomic instability which in turn creates an immunogenic environment for ICB." (PMID 36645718, 2023). "MYO10 promotes tumor progression by inducing genomic instability, which, in turn, creates an immunogenic environment for immune checkpoint blockades; when upregulated in both human and mouse tumors, its expression level predisposes tumor progression." (PMID 38248360, 2023). "Knockdown the expression of MYO10 alleviated tumor invasion and metabolic stress responses in glioblastoma." (PMID 35478939, 2022). "In KEGG analysis results, we noticed that MYO1B, MYO5A, and MYO10 associated DEGs were enriched in PI3K-Akt signaling, focal adhesion process, and ECM-receptor interaction which were all related to tumor metastasis." (PMID 35478939, 2022). "CAF-derived ANGPTL2, WWTR1, and PLOD2 promote tumor progression and cell invasion, and MYO10 regulates CAF rigidity." (PMID 33917869, 2021). "It is also possible that Myo10 has other cellular roles in the skin, for example during wound healing or tumour formation." (PMID 29509981, 2019). "For each tumor entity, patients were divided into two subgroups, MYO10 fold change <1 and MYO10 fold change >1, based on the expression ratio of MYO10 mRNA in tumor versus tumor-free tissue." (PMID 29934580, 2018). "Onset of tumors was delayed by Myo10 inactivation, and the average tumor volumes were also markedly reduced from day 30 in Tyr-CreER/PtenKO/BrafCA/Myo10KO mice." (PMID 29993000, 2018). "Recent data suggest that Myo10 determines tumour invasiveness and cell cycle regulation, leading us to suggest that it could exert these functions both in melanocytes and in other skin cell populations." (PMID 29509981, 2019). "In this list, we highlighted MYO10 and ADAM19, two genes linked to tumor aggressiveness." (PMID 30814494, 2019). "The tumor cells with mutated myosin X, lacking binding ability with integrin, decrease the formation of filopodia." (PMID 27121062, 2016). "MYO10 is overexpressed in EGFR-overexpressing GBMs52, and GBM mouse models indicate that MYO10 supports malignancy because knockout of MYO10 impairs GBM invasion, slows tumor proliferation, reduces integrin-related signaling and prolongs survival." (PMID 38773237, 2024). "DOCK11 showed significantly lower levels in tumor datasets, while MCAM, MYO10, and WASF3 exhibited significantly higher levels in tumor datasets, compared with the normal group." (PMID 34128858, 2021). "The close relationship between MYO10 and INF may exist not only in tumor tissues, but also in other tissues." (PMID 37214088, 2023). "In conclusion, this manuscript provided comprehensive analyses about the expression and function of MYOs in HNSCC, suggested MYO1B, MYO5A, and MYO10 as potential prognostic biomarkers in HNSCC, and revealed the potential novel roles of MYO1B, MYO5A, and MYO10 in tumor immune microenvironment." (PMID 35478939, 2022). "An intriguing but unexplored mechanism of MYO10-dependent regulation of CRC development could be suggested based on observed interactions between this actin motor and important tumor suppressors." (PMID 33670106, 2021).
tumor (continued). "A significant co-occurrence of an upregulation of the mRNAs of MYO10, MYH9, MYO1E and TGFB1 was observed in the LUSC patients of the TCGA cohort, suggesting that the exposure of tumor cells to elevated levels of TGFβ might have stimulated upregulation of motility and invasion-related myosins." (PMID 29934580, 2018). "Furthermore, the protein levels of MYO1B, MYO5A, MYO5C, and MYO10 in HNSCC tumor tissues and normal tissues were examined by Human Protein Atlas (HPA) database; consistently, the protein levels of MYO1B and MYO10 were dramatically enhanced in tumor tissues compared with normal tissues." (PMID 35478939, 2022).
neurodegenerative disease (1 paper, 2024). A disorder of the central nervous system characterized by gradual and progressive loss of neural tissue and neurologic function. "The unconventional actin molecular motor protein, Myosin-X (Myo10) is considered a key regulator in the formation of TNTs, enabling neuron-to-neuron transport and contributing to the spread of pathological proteins in neurodegenerative diseases." (PMID 39409126, 2024).
MYO10 also shares sentences with these, for which no sentence is quoted: infection (3 papers); cervical cancer (2); non-small cell lung carcinoma (2); squamous cell carcinoma (2); Alzheimer disease (1); astrocytoma (1); laryngeal squamous cell carcinoma (1); metastatic malignant melanoma (1); neuroblastoma (1); nevus (1); sarcopenia (1); Skin Cutaneous Melanoma (1); tobacco use disorder (1).